VEGFA (vascular endothelial growth factor A)
Diseases named in the same sentence as VEGFA in open-access papers (continued):
Sharing a sentence is not in itself a finding about the gene and the disease.
glioma (continued). "The results showed that expression levels of VEGFA, HK2, JUN, LDHA, and GAPDH were significantly high in glioma with wildtype-IDH and wildtype-1p/19q codeletion." (PMID 32500034, 2020). "To observe the clinical relevance of VEGFA, we first evaluated its mRNA expression in a cohort of 981 low- (LGG) and high-grade glioma (HGG) patients." (PMID 32564774, 2020). "miR-140-5p directly targets VEGFA and suppresses VEGFA/MMP2 signaling to inhibit angiogenesis in colorectal cancer and glioma cells." (PMID 32993787, 2020). "ANXA2P2 was positively correlated with genes that are related to glioma proliferation, invasion and angiogenesis, such as ANXA2, CD44, IL6, MMP14, MMP9, and VEGFA." (PMID 31681595, 2019). "Glioma cells can impair their antitumor function via Fas antigen ligand (FasL), programmed cell death 1 ligand (PDL-1), VEGFA, and EVs." (PMID 32038644, 2019). "Together with VEGFA, these factors were higher in GBM as compared to the lower-grade gliomas, illustrative of their correlation with tumor grade and level of glioma neovascularization." (PMID 31428150, 2019). "Most specifically, based on REMBRANDT data, SRSF1 mRNA was significantly upregulated in all glioma grades with respect to normal brain (p-value < 0.0001, ANOVA test), while VEGFA was significantly upregulated specifically in GBM (p-value < 0.0001, ANOVA test)." (PMID 30736462, 2019). "Vascular Endothelial Growth Factor-A (VEGF-A), GFAP and muscle-specific pyruvate kinase-M2 (PKM2) are upregulated in glioma, and the level of upregulation of VEGF, VEGF receptor 2 (VEGFR2), GFAP, and PKM2 correlate with tumor grade and lethality (review)." (PMID 26689994, 2016). "Inhibition of VEGF function by using Bevacizumab, a humanized monoclonal antibody against VEGFA, has received accelerated approval to target tumor angiogenesis in glioma patients." (PMID 27891292, 2016). "Purinergic signaling related genes such as GPR17, VEGFA and CCL2 are involved in inflammation leading to glioma growth." (PMID 27323413, 2016). "The overall results of this study revealed a role for EFEMP1 in the suppression of glioma growth, via independent blockade of EGFR and AKT signaling pathways and the repression of VEGFA-induced angiogenesis." (PMID 21955618, 2011). "We next focused our attention on the mechanism of increased VEGFA mRNA expression via UPR and hypoxia signaling pathways using the C6 rat glioma cell line." (PMID 20824063, 2010). "Both VEGFA and XBP1 expression increased significantly with glioma pathological grade." (PMID 40621799, 2025). "A unique understanding of the combination of anti-CD276 and anti-angiogenesis revealed by using antibody–drug conjugates to ablate CD276+glioma cells concurrently impairing tumour vascular, which was reinforced by the confirmation that CD276 was positively correlated with VEGFA and MMP2." (PMID 38523646, 2024). "IDO1-overexpression-derived-tryptophan depletion activated the general control nonderepressible 2 (GCN2) pathway and upregulated VEGFA in glioma cells." (PMID 39065567, 2024). "Here, we performed rescue experiments to investigate whether the miR‐101‐3p/EZH2/VEGFA axis, involved in the lncRNA SPRY4‐IT1, promoted glioma cells proliferation and induced angiogenesis." (PMID 36479622, 2023). "In the cancer-immunity cycle, we found genes that inhibit the cycle, including the glioma-secreted and cell-surface immunosuppressive factors, TGFB1, VEGFA, ARG1, IL10, and CD70, they were highly expressed in the high-risk group and were positively correlated with the risk score." (PMID 37891828, 2023). "Moreover, ELISA results indicated that VEGFA protein levels were downregulated and upregulated in SPRY4‐IT1‐silenced and ‐overexpressed glioma cells, respectively, compared to the control cells." (PMID 36479622, 2023). "Therefore, the rescue experiment results demonstrated that the effect of SPRY4‐IT1 on glioma cell proliferation and angiogenesis occurred partly through the miR‐101‐3p/EZH2/VEGFA axis." (PMID 36479622, 2023).
glioma (continued). "In light of these findings, combining anti-VEGFA and anti-MET treatments might clinically benefit MET-altered adult patients with pediatric glioma." (PMID 37214395, 2023). "In addition, we found that the expression levels of VEGFA, MMP2, and MMP9 were, unsurprisingly, downregulated after inhibition of AKT signaling, even in L1‐overexpressing glioma cells." (PMID 36708044, 2023). "Additionally, a predictive model based on five HUB genes (FABP5, VEGFA, SAA1, ADM, and PRLHR) was constructed to predict OS in patients with gliomas." (PMID 35800054, 2022). "Similarly, HOXC10 overexpression promotes angiogenesis in human gliomas through interaction with PRMT5 and upregulation of VEGFA expression in vitro." (PMID 36531217, 2022). "Although FOXM1B has been reported to increase VEGF transcription in glioma cells, we observed that only FOXM1D, but not FOXM1A/B/C caused a marked upregulation in VEGFA transcription as detected by quantitative real‐time PCR (qRT–PCR)." (PMID 33314660, 2021). "Moreover, circSCAF11 and circITGA7 can promote glioma angiogenesis and tumor occurrence through miR-421/SP1/VEGF and miR-34a-5p/VEGFA axis, respectively." (PMID 34745938, 2021). "Chloroquine, an anti-malarial drug, restricted glioma cell proliferation via suppression of TGF-β activity as well as expression of plasminogen activator inhibitor-1 (PAI-1) and vascular endothelial growth factor A (VEGF-A)." (PMID 34439380, 2021). "Additionally, we find that B7H3 is positively correlated with VEGFA and MMP2 by bioinformatics analysis in gliomas." (PMID 34079802, 2021). "In glioma, LINC01116 is overexpressed and can target VEGFA to promote the tumorigenesis of glioma." (PMID 33535997, 2021). "In human GBM, VEGFA, MMP-9, and MMP2 levels correlate with glioma progression and could be secreted by both tumour cells and MDSCs." (PMID 33452462, 2021). "MiR-526b-3p inhibited glioma angiogenesis via repressing MMP2 and VEGFA." (PMID 32600379, 2020). "The quantitative real-time PCR method was used to evaluate mRNA expression of SEMA3(A-G), neuropilins (NRP1 and NRP2), plexins (PLXNA2 and PLXND1), cadherins (CDH1 and CDH2), integrins (ITGB1, ITGB3, ITGA5, and ITGAV), VEGFA and KDR genes in 59 II-IV grade glioma tissues." (PMID 33036421, 2020). "circCPA4, circSCAF11, circ-PITX1 were significantly up-regulated in GBM, accelerated the glioma tumorigenesis via let7/CPA4, miR421/SP1/VEGFA, miR-379-5p/MAP3K2 axis, respectively, while CircMTO1 markedly down-regulated and inhibited GBM proliferation through miR92/WWOX pathway." (PMID 32061256, 2020). "Indeed, we observed significant negative correlations between ClockLoss and HIF-1A targets (CA9, VEGFA and LDHA) in glioma." (PMID 31014368, 2019). "VEGFA was identified as an activated UPR in CPA-treated GL261(B6) tumors, consistent with the requirement for VEGFA signaling via VEGFR2 for CPA/6d to induce immune cell recruitment in responding gliomas." (PMID 27515027, 2016). "Interestingly, as a known positive regulator, CCL19 demonstrated relatively more negative correlations in glioma, with the most significant negative correlations with VEGFA, CD276, and HMGB1." (PMID 40714831, 2025). "The immune infiltration analysis further indicated that M0 macrophages may participate in the regulation of the prognosis of VEGFA-XBP1.Hypoxia-induced ferroptosis modulation emerges as a prognostic factor in gliomas, with XBP1 and VEGFA representing druggable nodes for novel combination therapies." (PMID 40621799, 2025). "Our analysis suggests that VEGFA gain is not the only driver event in glioma recurrence, and targeting VEGFA alone may not fully reverse the effect of 6p gain in aneuploid cells." (PMID 37741941, 2023). "However, vascular endothelial growth factor A (VEGFA) specific inhibition had no significant impact in clinical practice of gliomas." (PMID 35629359, 2022).
glioma (continued). "Moreover, glioma A172 cells can also induce angiogenesis by secreting exosomes containing linc-POU3F3 and upregulate the expression level of angiogenesis-related genes such as bFGF, bFGFR, and VEGFA in human brain microvascular endothelial cells (HBMECs)." (PMID 33912560, 2021). "The results of HUVEC (human umbilical vein endothelial cell) tube formation assays showed that when Bevacizumab blocked the biological function of VEGFA, glioma cells overexpressing NKILA could not improve the angiogenic ability of endothelial cells as well." (PMID 32382013, 2020). "The pattern of TAM development in glioma started first with a microglia phenotype (P2RY12+/TMEM119+), then it turned to polarized macrophage (CD163+), and finally converged into M2b macrophages (IL1RN+) with activated expression of strong angiogenesis signaling molecules (VEGFA)." (PMID 34692159, 2020). "PAX6 suppresses glioblastoma cell growth, anchorage-independent growth and glioma angiogenesis as well as invasiveness of glioblastoma cell, via inhibition of matrix metalloproteinase-2 (MMP2) expression and vascular endothelial growth factor A (VEGFA) expression." (PMID 24454925, 2014). "Immunohistochemistry staining was employed to determine the expression levels of IDO1, VEGFA, and CD34 in paraffin-embedded tissue sections obtained from 5 non-glioma tissue donors and 13 glioma tissue donors." (PMID 39065567, 2024). "None of the twelve tumors (7 gliomas, 3 supratentorial PNETs, 2 ependymomas) tested with IHC displayed any NESP55 immunoreactivity in regions with hypoxia-induced VEGFA expression, or elsewhere in the tumors." (PMID 20862257, 2010). "In addition, our data confirm that there are positive correlations among FBXO22, HIF-1α, and VEGFA expression, and there is a negative correlation between FBXO22 and VHL protein expression in glioma patients." (PMID 38519492, 2024).
diabetic retinopathy (830 papers, 2007 to 2026). "Multiple candidate gene studies have suggested several loci that are associated with diabetic retinopathy including VEGFA, AKR1B1, AGER, ICAM1 and MTHFR." (PMID 37452207, 2023). "In contrast, VEGFA, polymorphisms of which have been linked to severity of Diabetic Retinopathy, was expressed at higher levels in the periphery compared to fovea." (PMID 32555229, 2020). "VEGFA codes for the protein “Vascular endothelial growth factor A”, and variants near VEGFA have been implicated in a range of clinical conditions, including diabetic retinopathy and age-related macular degeneration." (PMID 23861737, 2013). "Defects in VEGFA have been shown to be associated with diabetic retinopathy, diabetic nephropathy leading to end-stage renal disease and diabetic neuropathy." (PMID 23029515, 2012). "Furthermore, VEGFA has been associated with abnormal angiogenesis in various diseases, including cancer, diabetic retinopathy, and macular degeneration." (PMID 41007164, 2025). "Moreover, we found the dysregulated miR-195, YY1, VEGFA, and Snail1 were associated with diabetic retinopathy development." (PMID 34267179, 2021). "Additionally, it would be of interest to investigate if EPAC-1 activation can rescue the VEGFa-induced endothelial hyperpermeability, as this is not only associated to (diabetic) retinopathy, but also with endothelial hyperpermeability in tumors." (PMID 28353063, 2017). "In diabetic mice SIRT1 exerts an antiangiogenic role in diabetic retinopathy via microRNA (miR)-20a elevation and yes-associated protein/HIF-1α/vascular endothelial growth factor A (YAP/HIF-1α/VEGFA) downregulation." (PMID 41011644, 2025). "HIF-1α is particularly noteworthy as it directly upregulates VEGFA expression, linking hypoxia and angiogenesis pathways, which are central to the pathogenesis of diabetic retinopathy (DR)." (PMID 40002404, 2025). "Through intravitreal administration and in vitro mimic transfection, miR-205-5p effectively restored VEGFA levels and inhibited key processes such as angiogenesis and migration, which are central to the progression of diabetic retinopathy." (PMID 40002404, 2025). "MSC-Exos targeted integrin α1 (ITGA1) via the delivery of microRNA-192, leading to a significant reduction in angiogenesis-associated factors, including VEGFA and CD31, and mitigating Müller cell activation in diabetic retinopathy." (PMID 39984849, 2025). "Vascular endothelial growth factor-A (VEGF-A) is highly upregulated in diabetic retinopathy and induces the progression of various events characterizing the disease, including vascular leakage, neovascularization, and DME6." (PMID 38906906, 2024). "It was reported that VEGFA promotes angiogenesis, and abnormal levels of VEGFA expression can exacerbate pathological angiogenesis and the development of diabetic retinopathy." (PMID 36820318, 2023). "Hyperglycemia results in the overexpression of VEGFA, which is a critical factor in diabetic complications such as diabetic retinopathy and diabetic nephropathy." (PMID 36747287, 2023). "AKT1, SRC, and VEGFA were found to have the binding energy of < −5 kcal/mol with all key targets of diabetic retinopathy, suggesting the good binding energy towards the key targets of diabetic retinopathy." (PMID 36467890, 2022). "When exposed to hypoxic conditions, the antioxidant VEGFA is elevated, and this upregulation performs a critical function in developing diabetic retinopathy." (PMID 36333816, 2022). "Molecular docking confirmed a good binding affinity of active ingredients of Mingmu Dihuang pill, including luteolin, acacetin, naringenin, and alisol B, with AKT1, SRC, and VEGFA, three hub targets of diabetic retinopathy." (PMID 36467890, 2022). "VEGFA is considered a potential genetic candidate involved in type 2 diabetes and diabetic retinopathy progression." (PMID 35267929, 2022).
diabetic retinopathy (continued). "The hub target VEGFA is widely expressed in arterial, venous, and lymphatic microvessels and endothelial cells of large vessels, and VEGF inhibitors or anti-VEGR agents have been proven to be highly active against diabetic retinopathy." (PMID 36467890, 2022). "Molecular docking confirmed a good binding affinity of active ingredients of MMDHP, including luteolin, acacetin, naringenin, and alisol B, with AKT1, SRC, and VEGFA as the three key targets of diabetic retinopathy." (PMID 36467890, 2022). "Hyperglycaemia results in overexpression of VEGFA, which is a critical factor in diabetic complications such as diabetic retinopathy and diabetic nephropathy." (PMID 34675276, 2021). "Vascular endothelial growth factor-A (VEGF-A) has a pathologic role in microvascular diabetic complication, such as diabetic retinopathy (DR)." (PMID 33709000, 2021). "Hyperglycemic situations result in overexpression of VEGFA which is a critical factor in diabetic complications such as diabetic retinopathy." (PMID 33150068, 2020). "In eye diseases such as diabetic retinopathy, hypoxia and the ensuing increased production of VEGFA is accompanied by breakdown of the BRB." (PMID 32312382, 2020). "In particular, it has been demonstrated that HMGA1 regulates VEGFA gene expression in diabetic retinopathy and, by interacting with HIF1, in 3T3 L1 adipocytes." (PMID 31311575, 2019). "The present study explored the effect of miR-200b on the developmentof diabetic retinopathy (DR) by targeting vascular endothelial growth factor A(VEGFA) gene." (PMID 28122882, 2017). "Angiogenesis is associated with a number of pathological conditions, including tumor growth and diabetic retinopathy, and vascular endothelial growth factor-A (VEGF-A) promotes angiogenesis and also induces vascular permeability." (PMID 25255225, 2014). "VEGFA is a critical driver in these processes, acting as a vascular leakage inducer, angiogenesis mediator and neuron protector in diabetic retinopathy." (PMID 24618407, 2014). "The vascular endothelial growth factor (VEGFA) gene has been suggested to play an important role in the pathogenesis of diabetic retinopathy (DR)." (PMID 24131746, 2013). "Interestingly, RBP3 expression was inversely correlated with diabetic retinopathy, suggesting a protective effect against the disease potentially through interaction with vascular endothelial growth factor A (VEGF)." (PMID 40076480, 2025). "VEGFA and JUN were identified as the central players in diabetic nephropathy and Alzheimer’s disease whereas, VEGFA was associated with diabetic retinopathy, cardiac autonomic neuropathy, and non-alcoholic fatty liver disease-hepatocellular carcinoma." (PMID 36482897, 2022). "Then we explored how VEGFA and Snail1 were initiated in diabetic retinopathy." (PMID 34267179, 2021). "In addition, the vascular endothelial growth factor signaling pathway that involving many target proteins, such as INSR, NOS3, PTGS2, and vascular endothelial growth factor A (VEGFA), plays a key regulatory role in diabetic retinopathy." (PMID 32265717, 2020). "Although a chronic and sustained stimulation of upregulated VEGFA was proposed to be a causal effect, we think that this hypothesis remains controversial since upregulated VEGFA can also result in diabetic retinopathy by excessive angiogenesis." (PMID 31501519, 2019). "This has considerable therapeutic implications as current anti-VEGFA treatments against multiple froms of cancer (Bevacizumab, Avastin®) or diabetic retinopathies and macular degeneration (Ranibizumab, Lucentis®) potentially target both pro- and anti-angiogenic forms of VEGFA." (PMID 29746548, 2018). "Formononetin could also alleviate the retinal neovascularization of diabetic retinopathy by inhibiting VEGFA." (PMID 29051733, 2017). "In addition, VEGFA facilitated retinal vessel permeability in diabetic retinopathy." (PMID 34267179, 2021).